DDR1 (discoidin domain receptor tyrosine kinase 1)
Diseases named in the same sentence as DDR1 in open-access papers (continued):
Sharing a sentence is not in itself a finding about the gene and the disease.
tumor (continued). "However, the tumor-suppressive effect and immune response resulting from the combined treatment of targeting DDR1 and CIR have not been elucidated, particularly in HNSCC." (PMID 40993737, 2025). "Furthermore, pharmacological inhibition of DDR1 using the small-molecule inhibitor 7rh recapitulated these effects, demonstrating potent anti-proliferative and ferroptosis-inducing capabilities, enhancing CIR sensitivity to better control tumor progression." (PMID 40993737, 2025). "Also, the orientation of collagen fibers is crucial for DDR1 activation, for example wavy rather than aligned type III collagen is sensed by DDR1-expressing dormant tumor cell." (PMID 38907027, 2024). "Moreover, when tumor samples were stratified according to the immune phenotype, all tumor samples classified as immune-excluded were DDR1 high and most tumors classified as non-excluded were DDR1 low, confirming the role of tumoral DDR1 in immune exclusion." (PMID 37284199, 2023). "Our study showed that under certain conditions, the inhibition of DDR1, a potential therapeutic target in cancer treatment, might have negative effects, such as inducing a pro-tumorigenic tumor microenvironment." (PMID 38136314, 2023). "The expression of DDR1 mRNA and protein is prominently higher in early recurrent tumour samples than in nonrecurrent tumour samples, suggesting that DDR1 may be a predictor of early recurrence after hepatectomy." (PMID 37007062, 2023). "Interestingly, the tumor cells in two TNBC groups displayed different expression patterns of the critical immunotherapeutic targets, such as PD-1/L1, CTLA4, CD47, CDK4/6, PARP1/2 and DDR1/2." (PMID 36998014, 2023). "DDR1 immunolabeling in tumor stroma was weak or negative in all cases." (PMID 35205677, 2022). "Moreover, this miR has a significant tumor suppressive function in the invasion and metastasis of prostate and triple negative breast cancers regulating epithelial to mesenchymal transition (EMT) through the inhibition of the DDR1-ERK signaling axis." (PMID 35216319, 2022). "However, we did not investigate the effects of collagen type XI on lung tumor cells, which express DDR1 that is not present in CAFs and can therefore differently modulate the tumor-cell behavior." (PMID 36233024, 2022). "Given that DDR1 is actually not essential because DDR1-null mice does not impair embryonic development, it is likely that tumor cells may become addicted to the increased levels of oncogenic DDR1." (PMID 33976105, 2021). "In line with our findings in the metastatic cell line AGP-01, the median expression levels of both mRNA (measured by qPCR) and protein (assessed by Western blot) of FRK and DDR1 were higher in metastatic patient samples regardless of the tumor stage (P < 0.0001 Mann-Whitney U test)." (PMID 32082487, 2020). "Moreover, thorough microscopic analyses of lung tissue sections, and immunohistochemical staining for human DDR1 (data not shown), revealed no clear evidence of tumours cell nests within the lung parenchyma." (PMID 32047176, 2020). "Despite this, analysis of each MMP band in each of the three independent experiments showed that DDR1-IN-1 significantly reduced by ~ 25% the expression of the active MMP9 (~ 82KDa) in the secretomes from basal KCs cultures, and by ~ 50% in the secretomes from tumor-activated KCs." (PMID 33110221, 2020). "Furthermore, DDR1 has been reported to interact with TM4SF1 and to induce tumor metastasis." (PMID 31142317, 2019). "Cox proportional hazard models showed that DDR1 expression level is an independent marker of poor prognosis in stage IV patients and is not correlated with already described variables like tumour location, grade, number of metastatic sites and CMS transcriptional subtype." (PMID 29438985, 2018).
tumor (continued). "Using quantitative phosphoproteomics, we identified BCR as a new DDR1 substrate and demonstrated that nilotinib prevents DDR1‐mediated BCR phosphorylation on Tyr177, which is important for maintaining β‐catenin transcriptional activity necessary for tumour cell invasion." (PMID 29438985, 2018). "Notably, these studies provided the rationale for combinatorial approaches involving either inhibition of DDR1 and Notch signaling or inhibition of the FOSL1 target AURKA and MEK, both of which blocked tumor initiation and progression as well as induced tumor regression." (PMID 29455666, 2018). "Anlotinib suppressed tumor cell proliferation via inhibition of platelet-derived growth factor receptors α/β (PDGFR α/β), c-Kit, Ret as well as Aurora-B, c-FMS, and discoidin domain receptor 1(DDR1), which was a group of newly identified kinase targets involving the tumor progression." (PMID 27716285, 2016). "Tumor cells that undergo EMT are found to express less epithelial markers such as E-cadherin and cytokeratins but express more mesenchymal markers such as vimentin and N-cadherin, with a possible switch in DDR expression from DDR1 (epithelial) to DDR2 (mesenchymal)." (PMID 27014069, 2016). "Our hypothesis indicates this tumorigenic effect of DDR1 appears to be in part mediated via TGFBI downregulation, which reinforces the notion of a tumor suppressor role for TGFBI We have also demonstrated that exogenous TGFBI could recapitulate the phenotypes associated with DDR1 knockdown." (PMID 25369402, 2014). "Indeed, we found a positive correlation between the expression of DDR1 and MMP2 in our patient cohort (data not shown), further supporting the important role of DDR1 for tumor invasion." (PMID 20799954, 2010). "Furthermore, the tumor in our case also did not harbor alterations commonly reported in intracranial schwannomas, such as ARID1A/B, DDR1, or SOX10 mutations, suggesting that it might arise from a different mechanism than intracranial schwannomas." (PMID 40255822, 2025). "However, when collagen 1 ages, DDR1 no longer promotes apoptosis and the tumor keeps growing." (PMID 37284199, 2023). "The matrix-remodelling capabilities of CAF may also affect tumour proliferation; CAF-secreted collagens, collagen8A1 and collagen11A1, have been shown to modulate tumour cell growth through interaction with DDR1 (Discoidin domain receptor 1), which is overexpressed in HNSCC tissues." (PMID 35048030, 2021). "By immunohistochemistry, normal GCs lacked Type VI collagen, whereas both DDR1‐positive and DDR1‐negative DLBCL showed prominent deposition of Type VI collagen surrounding tumour cells." (PMID 40401507, 2025). "Then, we constructed a stable Ddr1‐KD MC38 cell line, showing no influence on tumor cell proliferation in vitro." (PMID 38953306, 2024). "The results indicated that DDR1, phosphorylated DDR1 and ARF6-GTP were significantly upregulated in tumor tissues compared with corresponding adjacent non-tumor tissues." (PMID 35140331, 2022). "In the absence of collagen and in the presence of IGFs, DDR1 enhances the IR-A and IGF-1R pathways, thereby increasing tumor cell migration and survival through the PI3K/AKT pathway and tumor growth through the Ras/Raf/MEK/ERK pathway." (PMID 33917302, 2021). "MDA-MB231 and MDA-453 were used as a positive control for DDR1 expression in tumor cells, while LX2 cells were used as a positive control for non-tumoral DDR1." (PMID 32090682, 2020). "DDR1 was significantly over-expressed in tumours relative to normal samples, and this was the case for both HPV-negative (p = 0.0006) and HPV-positive tumours (p = 0.0012)." (PMID 31717573, 2019). "A switch between DDR1 and DDR2 during tumor progression has been demonstrated, but it is not impossible that a switch between the different DDR1 isoforms during tumor progression may exist." (PMID 33917302, 2021).
tumor (continued). "In order to assess the relevance of these five kinases in gastric cancer tumors, we analysed the mRNA and protein levels in 200 biopsies from gastric cancer patients, revealing that transcript and protein levels of FRK, DDR1, SRC were elevated in metastatic tissues regardless of tumor stage." (PMID 32082487, 2020). "Thus, it will be interesting to evaluate the effects of other matrices such as Matrigel, which contains COL4, a ligand for DDR1 but not DDR2, to further address the specificity of DDR-ECM interactions in regulation of tumour growth." (PMID 32047176, 2020). "Although compounds like imatinib, nilotinib, and dasatinib have been identified as DDR1 inhibitors, their lack of specificity—stemming from their original design to target ABL kinases—limits their effectiveness, particularly within the complex tumor microenvironment." (PMID 40713963, 2025). "The authors found that in TNBC patient samples which have never received any treatment, the percentage of DDR1 positive cells in DDR1 high tumors inversely correlated with the abundance of infiltrating CD8+ T cells, which were circumscribed to the tumor margin rather than present in the tumor core." (PMID 37284199, 2023). "The decrease in CD8+ cytotoxic T cells, which play a vital role in directly attacking and eliminating cancer cells, suggests that the absence of DDR1 might impact the recruitment or proliferation of CD8+ cytotoxic T cells, leading to reduced tumor cell killing." (PMID 38136314, 2023). "Notably, consistent with the results obtained from PDAC, matrix metalloproteinase-cleaved COL-I rather than intact COL-I promoted DDR1 activity in HCC tumor cells, suggesting that targeting the components of cleaved COL-I-DDR1 signaling may provide an alternative therapeutic strategy for anti-HCC." (PMID 40248197, 2025). "Importantly, in animal models of PDAC, tumors derived from cancer cells lacking DDR1 had fewer NET-like structures and the animals experienced fewer liver metastases, suggesting that cancer cell-derived DDR1 contributes significantly to NET-induced tumor metastasis." (PMID 34237033, 2021).
cancer (194 papers, 2007 to 2026). A tumor composed of atypical neoplastic, often pleomorphic cells that invade other tissues. "We performed a pan-cancer analysis integrating bulk transcriptomic datasets, single-cell RNA sequencing, and pathway enrichment to evaluate DDR1 expression, genetic alterations, and its associations with immune cell infiltration and clinical outcomes." (PMID 40869052, 2025). "Aberrant DDR1 activation has been implicated in multiple cancers, including pancreatic, cervical, hepatic, and breast malignancies." (PMID 41394854, 2025). "Pan-cancer analysis reveals that the association between DDR1 expression and phenotypic outcomes is divergent and context-dependent." (PMID 40869052, 2025). "In the context of cancers, microenvironmental collagens are likely to activate cancer cell growth through the receptor of DDR1, as it is associated with the cell proliferation signaling molecules RAS, PI3K, NFκB, and STAT." (PMID 40025071, 2025). "DDR1 can also be expressed on CNS cells, and its increased expression has been associated with various types of cancers, suggesting a role for DDR1 in cellular proliferation." (PMID 39221072, 2024). "Discoidin domain receptor 1 (DDR1) was associated with cellular migration and invasion in several types of cancers." (PMID 39567474, 2024). "Blocking ECM signaling by targeting integrins and their associated FAK kinase, or DDR1/2 collagen receptors, also has broad potential to improve anti-cancer therapies." (PMID 36774337, 2023). "DDR1 expression was significantly associated with DNA methylation in 8 cancers, while there was a correlation between DDR1 expression and RNA methylation-related genes and mismatch repair gene in most cancers." (PMID 37031216, 2023). "Regarding the expression of DDR1, there was a significant association between DDR1 expression and carcinoma (P = 0.0056) where all cases were positive, and most of them exhibited moderate and strong expression (57.2%)." (PMID 37271822, 2023). "Previous studies demonstrated that DDR1 was overexpressed and linked to invasion and metastasis in a variety of cancers, such as gastric, bladder, and other cancers." (PMID 35935941, 2022). "While DDR1 and DDR2 have been linked to cancer progression and metastasis, a downregulation of DDR1 and concomitant upregulation of DDR2 has been explicitly observed in EMT." (PMID 36713812, 2022). "Some of the high scoring BioChIP-seq enrichment sites included genes that have been implicated in cancer metastases (DDR1, BMP4, and SMAD6), and cell cycle and survival (CDIP1 and PPP2R5A)." (PMID 36207293, 2022). "DDR1, expressed in many epithelial and carcinoma cells, has been linked to the invasion of cancer cells in 3D collagen, primarily by promoting the production of matrix metalloproteases (MMPs)." (PMID 33287446, 2020). "Analysis of the same database for DDR1 expression vs. NRAS mutational status showed DDR1 to be slightly downregulated in all NRAS-mutated cancers (effect size −0.26, p = 0.00053) and with a similar tendency (effect size −0.29, p = 0.065)." (PMID 33014862, 2020). "Among them, DDR1 appears as the most probable candidate, since the aberrant expression of DDR1 was associated with increased tumorigenicity in different cancer entities." (PMID 33287446, 2020). "Our data are supported by previous studies which showed high expression of DDR1 is associated poor patient prognosis in lung, pancreatic and gastric cancers." (PMID 31717573, 2019). "Several mechanisms have been reported to cause abnormal expression of DDR1 in cancer, such as somatic mutations, transcriptional regulation and microRNA (miRNA) regulation." (PMID 31253192, 2019). "DDR1 has been identified as a cancer‐associated receptor tyrosine kinase that is highly expressed in several malignancies relative to normal tissues." (PMID 31116512, 2019).
cancer (continued). "Given that loss of polarity and aberrant tissue organization is associated with various pathologies including cancer, it will be valuable to gain an in depth understanding of this role of DDR1 signaling." (PMID 30760555, 2019). "Recently, the potent kinase inhibitory activities of imatinib, nilotinib and dasatinibmay have therapeutic implications in treatment of cancers associated with pathological DDR1 activity." (PMID 31253192, 2019). "Several lines of evidence suggest that DDR1 is overexpressed in cancer cells and this upregulation is associated with aggressiveness." (PMID 29559654, 2018). "We have previously demonstrated that IGF-IR cooperates with the G-protein estrogen receptor (GPER) and the collagen receptor discoidin domain 1 (DDR1) that are implicated in cancer progression." (PMID 27384677, 2016). "DDR1 is expressed in many epithelial and carcinoma cells and has been associated with cancer cell invasion in 3D collagen mainly through the promotion of MMP production." (PMID 27391444, 2016). "Discoidin domain receptor 1 (DDR1), a collagen receptor tyrosine-kinase, is as well frequently overexpressed in cancer and implicated in cancer progression." (PMID 25840417, 2015). "Aside from its role in cancer, DDR1 has also been implicated in playing a key role in a variety of human diseases such as pulmonary fibrosis, pituitary adenoma, atherosclerosis, and congestive heart failure." (PMID 25369402, 2014). "DDR1 expression was positively or negatively associated with prognosis in different cancers." (PMID 37031216, 2023). "However, the stiffer B‐collagen favors RMS cell survival and proliferation through the activation of integrin β1, often associated with cancer cell survival, allowing cells to overcome the collagen‐DDR1 pro‐apoptotic signals." (PMID 35957513, 2022). "The Discoidin Domain Receptor 1 (DDR1) is one of the two members of a unique family of receptor tyrosine kinase receptors that signal in response to collagen, which has been implicated in cancer progression." (PMID 34548097, 2021). "Moreover, DDR1 is often dysregulated in cancer, and it has been implicated in various aspects of cancer progression, including cell proliferation and invasion, promotion of stem phenotype, metastasis, and modulation of chemotherapy response." (PMID 34206590, 2021). "In addition, it has been demonstrated that low expression of miR-486-3p or high expression of DDR1 are associated with a poor prognosis in various cancer types." (PMID 31253192, 2019). "DDR1 has been described as one of the major tyrosine kinase receptors able to be activated by several collagens, including collagen 1, and has been shown to be overexpressed and associated with bad prognosis in several cancer pathologies." (PMID 29872495, 2018). "DDR1 is also over-expressed in many cancers and it associates with the IGF-1R." (PMID 26191041, 2015). "Interestingly, Ddr1 has been implicated in a number of different human cancers, possibly enhancing cell proliferation via direct activation of canonical Notch1 signaling." (PMID 24391948, 2013). "DDR1 has been shown to be expressed in various human tumors including lung, breast, ovary, and brain and to be associated with the production of metalloproteinases and cancer cell invasion of stroma tissues during metastasis." (PMID 22567280, 2012). "Thus, DDR2 together with DDR1 may contribute to the activation of signaling pathways associated with interactions of carcinoma cells with both network-forming and fibrillar collagens, as they traffic through various matrix compartments." (PMID 33014862, 2020).